RNF152 (ring finger protein 152)
Description:
E3 ubiquitin-protein ligase that acts as a negative regulator of mTORC1 signaling by mediating ubiquitination of RagA/RRAGA and RHEB. Catalyzes 'Lys-63'-linked polyubiquitination of RagA/RRAGA in response to amino acid starvation, thereby regulating mTORC1 signaling. Also mediates monoubiquitination of RHEB, promoting its association with the TSC-TBC complex and subsequent inhibition. Also mediates 'Lys-48'-linked polyubiquitination of target proteins and their subsequent targeting to the proteasome for degradation. Induces apoptosis when overexpressed.
Synonyms: FLJ39176
Tractability: Antibody: UniProt predicts a signal peptide or a membrane-spanning region. PROTAC: UniProt records ubiquitination sites on it.
Gene: Protein-coding gene on chromosome 18 (61,808,067 to 61,895,097, reverse strand). Ensembl gene ENSG00000176641.
Subcellular location: Lysosome membrane
Pathways (Reactome):
Metabolism of proteins: E3 ubiquitin ligases ubiquitinate target proteins
Gene Ontology:
Molecular function: protein binding; small GTPase binding; ubiquitin protein ligase activity; ubiquitin-protein transferase activity
Biological process: cellular response to amino acid starvation; negative regulation of TORC1 signaling; positive regulation of autophagy; protein K48-linked ubiquitination; protein K63-linked ubiquitination; protein monoubiquitination; apoptotic process; protein ubiquitination; protein polyubiquitination
Cellular component: lysosomal membrane; lysosome; organelle membrane
Genetic constraint (gnomAD): Loss-of-function variants: 11 observed, 13.58 expected, observed/expected ratio (o/e) 0.81, 90% interval 0.51 to 1.34. The upper end of that interval is the gene's LOEUF score, 1.34, which puts it in group 5 of 6, group 1 being the genes least tolerant of losing a copy. Missense variants: 255 observed, 288.94 expected, observed/expected ratio (o/e) 0.88, 90% interval 0.8 to 0.98. Synonymous variants: 113 observed, 125.59 expected, observed/expected ratio (o/e) 0.9, 90% interval 0.77 to 1.05.
Homologues: Orthologues: chimpanzee RNF152 (100% identical), macaque RNF152 (99% identical), guinea pig RNF152 (98% identical), mouse Rnf152 (98% identical), rat Rnf152 (98% identical), pig RNF152 (97% identical), rabbit RNF152 (96% identical), tropical clawed frog rnf152 (89% identical), zebrafish rnf152 (57% identical). Paralogues in human: SPRYD4 (14% identical), RNF135 (12% identical), RFPL1 (10% identical), RFPL4A (10% identical), RFPL4AL1 (10% identical), RFPL2 (9% identical), RFPL3 (9% identical), RFPL4B (7% identical), CD274 (6% identical), CD86 (6% identical), CD80 (3% identical), PDCD1LG2 (3% identical).
Diseases named in the same sentence as RNF152 in open-access papers:
RNF152 is named in the same sentence as 8 diseases in open-access papers, as found by Europe PMC text mining. Sharing a sentence is not in itself a finding about the gene and the disease. The quoted sentences say what the papers report.
colorectal cancer (4 papers, 2021 to 2025). A primary or metastatic malignant neoplasm that affects the colon or rectum. "RNF152 is associated with breast, prostate, and colorectal cancer." (PMID 38534778, 2024). "RNF152 is known to be downregulated in several biliary tract cancers, including hepatocellular carcinoma and colorectal cancer." (PMID 38706841, 2024). "RNF152 has been reported to play a role in tumors and over-expression of RNF152 inhibited colorectal cancer cell proliferation that was dependent on its E3 ligase activity." (PMID 33602225, 2021). "Similarly, the expression of RNF152 in colorectal cancer (CRC) tissues is considerably lower than its expression in adjacent noncancerous tissues." (PMID 40535770, 2025). "In colorectal cancer (CRC), overexpression of RNF152 has been show to inhibit CRC cell proliferation both in vitro and in vivo by inactivating the mechanistic target of rapamycin complex 1 (mTORC1) via targeting RagA for K63-linked ubiquitination and inducing autophagy and apoptotic cell death." (PMID 33602225, 2021).
liver cancer (2 papers, 2019 to 2023). An epithelial or non-epithelial malignant neoplasm that arises from the liver. "In an attempt to clarify the biological significance of RNF152 in tumor growth, we analyzed the expression levels of RNF152 by searching TCGA database and found that RNF152 is down-regulated in various types of cancers, including colon, lung, kidney, and liver cancers." (PMID 30514904, 2019). "PLK3, C9orf72, TRIM22, RNF152, FEZ1 and MEFV were dramatically downregulated in liver cancer patients, but upregulated by CTD treatment in HCC cells." (PMID 38017425, 2023).
biliary tract cancer (1 paper, 2024). "Therefore, in this study, we examined the effects of fasting on RNF152, a ubiquitin ligase that is downregulated in several biliary tract cancers." (PMID 38706841, 2024).
gallbladder cancer (1 paper, 2024). "We report that RNF152 regulates mTORC1 signaling by targeting a Ragulator subunit, p18, and attenuates gemcitabine resistance in gallbladder cancer (GBC)." (PMID 38706841, 2024).
cancer (4 papers, 2019 to 2024). A tumor composed of atypical neoplastic, often pleomorphic cells that invade other tissues. "Increasing evidence suggests that RNF152 can suppress the proliferation of cancer cells by regulating mTORC1 through a mechanism involving ubiquitination." (PMID 38706841, 2024). "RNF152 levels were significantly lower in GBC than in adjacent non-cancer tissues." (PMID 38706841, 2024). "When these cancer cells were transplanted in mice to create a xenograft model of GBC, fasting and the overexpression of RNF152 resulted in tumors with a smaller mass." (PMID 38706841, 2024).
tumor (4 papers, 2019 to 2025). "In our study, RNF152 was downregulated in the tumor tissue of GBC patients and in proliferating GBC cells." (PMID 38706841, 2024). "Staining by immunohistochemistry (IHC) detected higher levels of RNF152 in normal tissues than in tumor tissue." (PMID 38706841, 2024). "Fasting combined with the implantation of RNF152-overexpressing GBC-SD cells had the most obvious inhibitory effect on tumor growth in the mice." (PMID 38706841, 2024). "To determine the status of RNF152 in GBC we measured levels of expression in the tumor tissues of 25 patients with GBC and examined its correlation with clinical parameters." (PMID 38706841, 2024). "Representative tumor samples stained for the expressions of Ki-67 indicate that the overexpression of RNF152 results in a lower level of cell proliferation and increased sensitivity to GEM." (PMID 38706841, 2024). "Representative IHC images indicate low levels of RNF152 and high levels of p18 expression in GBC tissues, whereas high levels of RNF152 and low levels of p18 expression are found in non-tumor tissues." (PMID 38706841, 2024). "Our results showed that silencing the expression of TSPAN12 antagonized the enhancement of the in vivo HCC tumor growth induced by RNF152 depletion." (PMID 33602225, 2021). "Collectively, our data revealed a tumor suppressor role of RNF152 and a connection between RNF152 and FoxO1 in HCC." (PMID 33602225, 2021). "In summary, we have revealed a tumor suppressor role of RNF152 and a connection between RNF152 and FoxO1 in HCC." (PMID 33602225, 2021). "Both fasting and RNF152 overexpression inhibited tumor growth." (PMID 38706841, 2024). "Together, these data indicate a tumor suppressor role of RNF152 in HCC." (PMID 33602225, 2021). "Importantly, silencing the expression of TSPAN12 antagonized the enhancement of the HCC cell growth, colony formation, and invasion in vitro as well as HCC tumor growth in vivo induced by RNF152 depletion." (PMID 33602225, 2021). "Tumor volume indicates that fasting can enhance sensitivity to GEM, however when the expression of RNF152 is inhibited in tumors, the resistance to GEM is increased." (PMID 38706841, 2024). "In this study, we uncovered a tumor suppressor role of RNF152 in HCC and found that RNF152 is down-regulated and essential to inhibit the proliferation and invasion of HCC via TSPAN12 degradation." (PMID 33602225, 2021). "In summary, these data indicate that both RNF152 and USP4 play important roles in tumor growth via regulating mTORC1 activation." (PMID 30514904, 2019). "Our data showed that SW620 cells lacking RNF152 exhibited strong ability to form tumor with a rapid growth rate, which could be abolished by rapamycin treatment." (PMID 30514904, 2019).
RNF152 also shares sentences with these, for which no sentence is quoted: hepatocellular carcinoma (2 papers); melanoma (1).